MYC (MYC proto-oncogene, bHLH transcription factor)
Diseases named in the same sentence as MYC in open-access papers (continued):
Sharing a sentence is not in itself a finding about the gene and the disease.
Burkitt lymphoma (continued). "The P493-6 cell line, an EBV immortalized B lymphocyte engineered with a tetracycline (Tet)-repressible c-MYC expression vector, is considered as an in vitro Burkitt's lymphoma model." (PMID 18628958, 2008). "The biopsy was positive for c-MYC with “starry sky” appearance, all indicative of Burkitt lymphoma." (PMID 41191884, 2025). "These oncogenes can form through changes such as chromosomal translocation (e.g., chromosomal translocation of the MYC oncogene in Burkitt’s lymphoma), point mutation (e.g., point mutation at codon 12 of the RAS oncogene), and gene amplification (e.g., amplification of c-MYC in neuroblastoma)." (PMID 40563443, 2025). "Since c-MYC is highly activated in Burkitt lymphoma, circPVT1 may rely on c-MYC to drive proliferation." (PMID 40703518, 2025). "Indeed, prior studies showed that HMGA1 binds directly to the MYC promoter and induces cMYC in embryonic stem cells and iPSCs and, conversely, that HMGA1 is induced by cMYC in other settings (Burkitt lymphoma cells, transformed fibroblasts)." (PMID 40076747, 2025). "Additionally, we assessed the expression levels of c-MYC, a gene known to be overexpressed in Burkitt’s lymphoma and recognized as an important therapeutic target." (PMID 40308579, 2025). "To evaluate the extent to which H-DNA accumulates oxidative damage relative to B-DNA, we first performed an immuno-slot blot assay using a substrate with an H-DNA-forming sequence from the human c-MYC promoter that maps to a translocation breakpoint hotspot in Burkitt lymphoma." (PMID 39950343, 2025). "Indeed, repression was muted in BCL6-high Burkitt’s lymphoma cell lines (DAUDI and RAJI) with the characteristic chromosomal rearrangement of one or both alleles of the c-MYC promoter to the immunoglobulin heavy chain regulatory region." (PMID 40166243, 2025). "To investigate this and identify appropriate cell lines for further in vitro studies, we examined TdT expression in ten DLBCLs (including five cell lines with MYC/BCL2‐DH and an additional line with MYC translocation) and one Burkitt lymphoma cell line by immunocytochemistry." (PMID 41047873, 2025). "The MYC G4 is located immediately upstream (~100 bp) of the MYC P1 promoter, generally responsible for 15 to 20% of total MYC expression though can be greater in some cell types and is up-regulated in cancers such as Burkitt’s lymphoma (28, –30)." (PMID 38315865, 2024). "We previously showed in models of MYC amplification representing liver cancer (tumors and cell lines) and Burkitt’s Lymphoma that suppressing amplified MYC leads to changes in clock gene expression, including increasing BMAL1 (which suggested that MYC suppressed BMAL1 in these settings)." (PMID 37639465, 2023). "In Burkitt’s lymphoma, bortezomib downregulates MYC expression." (PMID 37173935, 2023). "Through PRECOG, we found that high ST6GALNAC4 expression, among all sialyltransferases, is the strongest predictor of adverse patient outcomes in diffuse large B-cell lymphoma (DLBCL), chronic lymphocytic lymphoma (CLL), and Burkitt lymphoma (BL), which notably all have high MYC activity." (PMID 36897988, 2023). "We chose Ramos Burkitt’s lymphoma cells, which are transformed due to MYC overexpression." (PMID 37768948, 2023). "To test whether the molecular insights gained using HLH* EIF3A could have physiological implications in cancer, we generated HLH* EIF3A expressing Ramos Burkitt’s lymphoma cell lines, which are dependent on MYC overexpression for their proliferation." (PMID 37768948, 2023). "As expected, MYC-Ctr was inactive in Namalwa Burkitt lymphoma cells." (PMID 37225982, 2023).
Burkitt lymphoma (continued). "In order to verify the hypothesis that AL928768.3 influences the expression of MYC in Burkitt lymphoma cells, we used Namalwa cell line, which is a Burkitt lymphoma carrying an IGH/MYC translocation." (PMID 35563017, 2022). "We conducted a search for the eRNAs that may affect MYC transcription in the case of IGH/MYC translocation in Burkitt lymphoma, looking for potentially oncogenic eRNAs located at the IGH locus and predominantly expressed in B cells." (PMID 35563017, 2022). "In a MYC-transformed Burkitt lymphoma (BL) model, inhibiting LDH led to tumor reduction in vivo." (PMID 35204484, 2022). "In Burkitt’s lymphoma (BL) cells that have a c-MYC chromosomal translocation to one of the immunoglobulin (IG) loci on chromosomes 2, 14, or 22, the transcription of a c-MYC proto-oncogene is characterized by preferential transcription from the c-MYC promoter P1." (PMID 35740961, 2022). "DNMT1 and DNMT3B show MYC-dependent overexpression in Burkitt’s lymphoma (BL)." (PMID 35463343, 2022). "It was proposed that EBV may participate in Burkitt’s lymphoma development in the case of MYC translocation." (PMID 35563017, 2022). "However, it is also a known proto-oncogene, so unsurprisingly, EBNA2-mediated MYC activation seems to promote lymphomagenesis in Burkitt lymphoma." (PMID 36389670, 2022). "This leads to constitutive expression of MYC in Burkitt’s lymphoma." (PMID 34066504, 2021). "Strong evidence showing MYC’s role in human cancer was first found in Burkitt lymphoma." (PMID 34372899, 2021). "A study suggested that MYC translocation by itself does not cause Burkitt lymphoma, arguing that inhibitor of DNA binding (ID) proteins are another key factor." (PMID 34372899, 2021). "Indeed, HIV-Nef significantly promotes AICDA expression along with MYC expression in Burkitt lymphoma." (PMID 33557396, 2021). "Finally, the EBV pro-survival BCL-2 homologue, BHRF1, enhanced MYC activity in a mouse model of Burkitt’s lymphoma." (PMID 34066504, 2021). "Indeed, some of the earliest connections among the higher expression of proto-oncogenes (such as MYC), genetic rearrangements and their relation to cancer development were made in Burkitt lymphoma, chronic myeloid leukemia and mouse plasmacytomas." (PMID 35582389, 2021). "Burkitt lymphoma invariably shows a translocation of MYC gene to the immunoglobulin gene loci." (PMID 34372899, 2021). "MYC and ID3 were identified as the most mutated genes in Burkitt lymphoma." (PMID 34372899, 2021). "Recently, many studies have found that inhibition of bromodomain-containing protein 4 (BRD4) with pharmacological BET-specific bromodomain (BD) inhibitors can effectively block MYC expression in multiple myeloma, acute myeloid leukemia, and Burkitt's lymphoma 27-29." (PMID 32929368, 2020). "In Burkitt lymphoma, in which both MYC and HIF1α are highly expressed, HIF1α can actually collaborate with MYC to induce the expression of specific target genes, such as HK2, PDK1, and vascular endothelial growth factor (VEGF) under hypoxia and confer resistance to cisplatin treatment." (PMID 33251216, 2020). "Nevertheless, approximately 10% of Burkitt lymphoma can lack an identifiable MYC rearrangement, and in the presence of strong c-Myc expression by immunohistochemistry, it suggests an alternative mechanism of MYC gene deregulations." (PMID 33322508, 2020). "Besides CLL and MCL cell lines, we included three additional cell lines with activating MYC-fusions (Burkitt lymphoma cell lines RAMOS, DAUDI, VAL)." (PMID 32555249, 2020).
Burkitt lymphoma (continued). "Together, these results indicate that TET1 expression is high, while TET2 is low in T-ALL derived from EμSRα-tTAα;tet-o-MYC and in human Burkitt lymphoma, revealing a direct correlation between MYC and TET1, and an inverse correlation between MYC and TET2 expression levels." (PMID 31266538, 2019). "Since MINCR is a MYC-induced lncRNA, and has been reported to modulate c-Myc’s transcriptional network in Burkitt lymphoma cells, we sought to determine whether the function of MINCR may associated with the expression of c-Myc and its downstream genes." (PMID 31481083, 2019). "Additionally, human MYC-dependent models, such as the Burkitt lymphoma cell-line model P493-6 with the ability to regulate MYC levels, have been used extensively to interrogate transcriptional regulation by MYC." (PMID 31350286, 2019). "Interestingly, GCN5 has also been linked to PI3K signaling, which works synergistically with MYC in Burkitt lymphoma." (PMID 31645904, 2019). "In fact, deregulation of c-MYC expression is observed in more thanhalf of human cancers and oncogenic MYC has been associated with aggressivebreast, prostate, and colon cancers, as well as Burkitt lymphoma." (PMID 31930281, 2019). "Similarly, we previously reported that in T-ALL and Burkitt lymphoma MYC directly controls the overexpression of DNMT3B for tumor maintenance, maintaining specific 5mC and thus gene expression patterns." (PMID 31266538, 2019). "Furthermore, using co-immunoprecipitation we demonstrated a direct interaction between MYC and HSP90, indicating that MYC is an HSP90 client protein in Burkitt lymphoma." (PMID 30453475, 2018). "Together, our findings suggest that targeting MYC indirectly by inhibiting the HSP90 machinery, using 17-DMAG as a potential chemotherapeutic drug, may be an alternative therapeutic strategy for Burkitt lymphoma and possibly other MYC-associated cancers." (PMID 30453475, 2018). "Moreover, MYCMI-6 significantly inhibited growth of Burkitt’s lymphoma (BL) cells - another classical example of a MYC-driven tumor, having translocations of MYC to one of the immunoglobulin loci - in a dose-dependent manner with an average GI50 of 0.5 μM." (PMID 29968736, 2018). "Since MYC has been reported to be a client of HSP90 in mantle cell lymphoma, and HSP90 inhibition caused protein destabilization of MYC and NMYC in neuroblastoma, we speculated that the MYC-HSP90 axis might also be critical in Burkitt lymphoma." (PMID 30453475, 2018). "Considering both transcriptional and post-translational mechanisms of action, we found that 17-DMAG treatment caused changes in the transcriptional regulation of the translocated MYC gene in Burkitt lymphoma cells, revealing a shift from active to inactive chromatin structure." (PMID 30453475, 2018). "Finally, we note that GQC-05 was originally selected as a compound that bound to a DNA G4-forming sequence in the MYC promoter and induced apoptosis in a Burkitt's lymphoma (BL) cell line." (PMID 29156002, 2018). "Dysregulation of the MYC gene is a defining molecular marker of Burkitt's lymphoma." (PMID 29593916, 2018). "In Burkitt's lymphoma, reciprocal translocation shifts c-MYC-NHE III1 under the control of an ectopic promoter (in Ramos cells) or leads to a Pu27-deleted c-MYC allele (in CA46 cells) resulting constitutive c-MYC transcription." (PMID 30239898, 2018). "Furthermore, Co-IP analysis indicates that in Burkitt lymphoma MYC protein exists in complex with HSP90." (PMID 30453475, 2018). "Together, we conclude that MYC is a client protein of HSP90 in Burkitt lymphoma." (PMID 30453475, 2018). "Consequently, gene expression profiling experiments were conducted in LAT1 null and MYC null cells (Burkitt’s lymphoma cells)." (PMID 30103560, 2018). "Indeed, the early analysis of MYC dysregulation in Burkitt’s lymphoma revealed the importance of transcriptional regulation post-initiation, with precocious Pol II escape associated with MYC-driven pathology." (PMID 28398229, 2017).
Burkitt lymphoma (continued). "P493-6 cells served as a model for MYC activation in Burkitt’s lymphoma." (PMID 29100357, 2017). "Further examination of the underlying regulatory mechanism in T-ALL and Burkitt’s lymphoma revealed a direct correlation of DNMT1 and DNMT3B expression with high MYC levels, which led us to assess whether transcriptional regulation is MYC-dependent." (PMID 29100357, 2017). "Azacytidine and decitabine might be promising therapeutic strategies for translocated MYC, found not only in Burkitt’s lymphoma, but also in some diffuse large B-cell lymphoma (DLBCL) and other types of non-Hodgkin lymphoma." (PMID 28505071, 2017). "The glutamine-addiction of MYC transformed cells provides possible therapeutic opportunities and for example, pharmacologic inhibition of GLS1 has been shown to inhibit tumor progression in mouse models of MYC-driven Burkitt's lymphoma or hepatocellular carcinoma." (PMID 28443281, 2017). "Lactate dehydrogenase A (LDH-A), which is frequently overexpressed in numerous human cancers, was also identified as a MYC target gene in fibroblasts, and its over-expression was shown to be required for MYC-mediated transformation of human lymphoblastoid cells and Burkitt lymphoma cells." (PMID 28362357, 2017). "Downregulation of STAT1 by c-MYC overexpression observed in the current study is also detected in Burkitt’s lymphoma, supporting the concept that immune escape of tumor cells could be promoted by activation of a cellular oncogene." (PMID 27198694, 2016). "Additionally, let-7a reportedly inhibits MYC-induced cell growth in Burkitt lymphoma cells by blocking MYC expression." (PMID 26399619, 2016). "EBV-driven MYC enhancer activation may contribute to the genesis and localisation of MYC-Immunoglobulin translocation breakpoints in Burkitt's lymphoma." (PMID 27490482, 2016). "MYC was predicted by xseq for 11 samples, 10 of which are Burkitt lymphomas." (PMID 25903198, 2015). "Notably, a substantial genomic instability is also found, characterised by a high degree of MYC-Igh related translocations that are well known as transformation events in Burkitt’s lymphoma." (PMID 25232701, 2014). "The present case demonstrates that Burkitt lymphoma morphology can be associated with MYC translocations that do not involve the immunoglobulin loci." (PMID 25349747, 2014). "JQ1 was highly effective against preclinical models of several types of cancers with recurrent MYC amplifications, including acute myeloid leukemia, Burkitt's lymphoma and multiple myeloma, and efficacy was directly related to the extent of MYC suppression by treatment." (PMID 24231268, 2013). "Integration of oncogenic DNA viruses, such as of human papillomavirus (HPV) in most invasive genital cancers, Epstein-Barr virus (EBV) in infected lymphoblastoid cells or Burkitt’s lymphoma (BL), and adeno-associated virus (AAV) targeting MYC locus, have been well documented." (PMID 22580498, 2012). "Human Burkitt lymphoma (BL) is characterized in most cases by reciprocal chromosomal translocations that juxtapose the MYC proto-oncogene with immunoglobulin (Ig) heavy chain or light chain regulatory sequences resulting in deregulation of MYC transcription." (PMID 22754359, 2012). "Burkitt's Lymphoma characteristically has a translocation involving a deregulated, activated, MYC gene on chromosome 8 and immunoglobulin genes on chromosome 14, or, more rarely, chromosomes 2 or 22, though alternative pathogenetic mechanisms leading to MYC activation have also been described." (PMID 22593768, 2012). "A well-known human disease involving c-MYC is human Burkitt's lymphoma, in which c-myc is translocated from chromosome 8 to one of three chromosomes that contain antibody-encoding genes where its transcription is activated by those strong lymphocyte specific promoters." (PMID 20066163, 2009).
Burkitt lymphoma (continued). "We used a series of transgenic mice that allowed cooperation between either the constitutive or antigen-activated BCR with the proto-oncogene MYC, the activation of which by chromosomal translocation has been implicated in the genesis of human diffuse large B cell lymphoma and Burkitt lymphoma (BL)." (PMID 18578569, 2008). "Indeed, 80% of the translocations in Burkitt's lymphoma juxtapose MYC to the immunoglobulin heavy chain locus, with MYC being overexpressed as a consequence." (PMID 18194563, 2008). "Burkitt lymphoma (BL) is a highly aggressive B-cell non-Hodgkin lymphoma (NHL) whose hallmark is the translocation and dysregulation of the MYC gene." (PMID 40951016, 2025). "Burkitt lymphoma (BL) is an aggressive non-Hodgkin B cell lymphoma with the potential to involve multiple organ systems, characterized by the translocation of the MYC oncogene." (PMID 39851582, 2024). "We previously showed that MYC promoted Burkitt lymphoma (BL) growth by inhibiting the tumor suppressor miR-150, resulting in release of miR-150 targets MYB and ZDHHC11." (PMID 38627588, 2024). "Constitutively high levels of MYC expression can result from translocations that juxtapose the MYC gene locus with other enhancer regions such as the immunoglobulin (Ig) heavy chain enhancer as in Burkitt lymphoma, or through complex chromosomal rearrangements as in the case of multiple myeloma." (PMID 39031286, 2024). "In line with endemic and sporadic BL, the rearrangement of the MYC gene on chromosome 8 is a nearly universal occurrence in HIV-associated Burkitt lymphoma." (PMID 39329948, 2024). "Burkitt lymphoma (BL) is a highly aggressive B-cell non-Hodgkin’s lymphoma that is characterized by the translocation and dysregulation of the proto-oncogene MYC as well as hypermutated immunoglobulin gene sequences." (PMID 37370963, 2023). "In Burkitt lymphoma (BL), a tumor of germinal center B cells, the pro-apoptotic properties of MYC are controlled by tonic B cell receptor (BCR) signals." (PMID 37546418, 2023). "Likewise, in B-cell malignancies, proto-oncogenes are often translocated to the locus of the immunoglobulin heavy chain (IGH), such as MYC in Burkitt lymphoma (IGH/MYC), CCND1 in mantle cell lymphoma, BCL-6 in diffuse large B-cell lymphoma (DLBCL) and BCL-2 in follicular lymphoma." (PMID 35563017, 2022). "We mined gene expression datasets in the B-cell line P493–6, which carries a conditional c-Myc allele that can be experimentally turned on (MYChigh), mimicking overexpression of the MYC transcription factor that is the driving oncogenic event in Burkitt’s lymphoma." (PMID 33720010, 2021). "MYC, a transcription factor, was first identified in Burkitt lymphoma (BL) but is expressed in all lymphomas (not only in BL) and affects the expression of several genes, leading to the development of many neoplasms." (PMID 34034760, 2021). "The IGH/MYC translocation that is signature of Burkitt lymphoma (BL) has a frequency that is correlated with AID activity level." (PMID 34135887, 2021). "For those carrying single MYC-trans signatures, 8 of 20 cases were affected by ID3-TCF3-CCND3 pathway mutations, which were prevalent in Burkitt lymphoma (BL)." (PMID 32736575, 2020). "Using a Burkitt lymphoma-like gene expression signature, we recently defined a high-risk molecular high-grade (MHG) group mainly within germinal centre B-cell like diffuse large B-cell lymphomas (GCB-DLBCL), which was enriched for MYC/BCL2 double-hit (MYC/BCL2-DH)." (PMID 31844144, 2020). "Moreover, the findings that some type of retroviruses expressing MYC provoke the formation of hematopoietic tumors, such as myeloid leukemia, and that its expression is deregulated in Burkitt lymphoma, reinforced the idea of the potential involvement of MYC in hematopoiesis." (PMID 32102485, 2020).